IGF1R (insulin like growth factor 1 receptor)
Diseases named in the same sentence as IGF1R in open-access papers (continued):
Sharing a sentence is not in itself a finding about the gene and the disease.
cancer (continued). "IGF1 enhances the hypoxic response by stabilizing HIF-α and upregulating VEGF-A.A functional cooperation between the IGF1R and VEGF pathways has been identified in cancer cells." (PMID 36479090, 2022). "We treated cells with cisplatin or ME or both, and the expression of cancer pathway factors including MYC1, HSP90AB1, and IGF1R was assessed." (PMID 36362498, 2022). "Another genetic recombinant approach fused Gel with the anti-insulin-like growth factor-1 receptor (IGF-1R), a 58 amino acid long peptide that can specifically bind to receptors, overexpressed in cancer cells." (PMID 35744957, 2022). "With the discovery of the important cancer-promoting protein IGF-1R, many targeted drugs of IGF-1R have been continuously developed and gradually applied to disease treatment." (PMID 35680570, 2022). "Quantitative differences in protein biomarker expression were found between liver and lung metastases, showing a significantly higher proportion of IGF-1R-, EGR-R-, CD44v6-, α2β1-, and PD-L1-positive cancer cells in the lung." (PMID 35454846, 2022). "IGF1 specifically binds to the membrane receptor IGF1R and activates the intracellular insulin receptor substrate (IRS), which in turn activates the PI3K/AKT pathway and promotes cancer development." (PMID 36620587, 2022). "Following our analysis of cancer hallmarks from the perspective of the IGF1 signaling pathway, it is relevant to question what was the rationale behind the identification of IGF1R as a therapeutic target." (PMID 36479090, 2022). "Metformin inhibits cancer cell proliferation by reducing the expression of EGFR and blocking signaling through IGF-1R." (PMID 36430639, 2022). "Recent research showed that miR-375 is strongly downregulated in a wide range of cancers and that it suppresses carcinogenesis by targeting various critical oncogenes including AEG-1, YAP1, IGF1R, and PDK1." (PMID 36157234, 2022). "IGF-1 receptor (IGF-1R) inhibitors prevent binding of IGF-1 to IGF1R and subsequently inhibit down stream signaling, including PI3K/Akt pathway, exerting antitumor activity and being potential targets for cancer treatment." (PMID 35126480, 2022). "By regulating the bioavailability of the type-1 IGF receptor (IGF1R) ligands, IGF-1 and IGF-2, the IGF binding proteins (IGFBP-1 to -6) play essential roles in cancer progression." (PMID 35597813, 2022). "ErbB3/HER3 overexpression is associated with lung, colon, gastric, and other cancers and has been also found to be responsible for resistance to HER2, IGF1R, and EGFR inhibitors in the treatment of several types of cancers." (PMID 35938171, 2022). "INSR and IGF1R belong to Insulin/IGF System, which was known to affect the malignant behavior of cancer cells and was regulated by Glycans." (PMID 35752862, 2022). "In other words, GnRH, IGF‐1R, or p120 catenin might be with very low basal level or loss of function in other cancers, leading to the disruption of this pro‐metastatic signaling, therefore P‐cadherin failed to activate metastasis in such cancers." (PMID 35601657, 2022). "Overall, this research sheds new light on the interrelationship between the IGF-1R/PI3K/mTOR and YAP/TAZ cancer-related pathways." (PMID 35284040, 2022). "The IGF-1R shows a high degree of homology with the insulin receptor and hybrid IGF-1R/insulin receptor species have been reported in cancers." (PMID 36497428, 2022). "Pancreatic fibroblasts have been reported to increase cancer dissemination and motility mediated by IGF1/IGF1R signaling under hypoxia, which is also reported to increase PI3K/Akt activity in fibroblasts as was observed in these data." (PMID 35565326, 2022). "Aberrant IGFBPs modulation leads to increased IGFs bioavailability and binding to the IGF1R or the IR-A and contributes to IGF dysregulation in cancer." (PMID 34440844, 2021).
cancer (continued). "Suppression of the expression level of Nrf2 via applying a CRISPR/Cas9 genome editing system illustrated that ERBB3 and IGF1R signaling pathway accompanied by thioredoxin and peroxiredoxin proteins play an effective role in KEAP1-mutant cancer cells." (PMID 33768092, 2021). "These were novel findings that show how insulin and IGF1 downstream signaling cascades differ in cancer cells; however, the mechanisms for these differences were obfuscated by the distance of E-cadherin and ACC from the InsR and IGF1R signaling pathways." (PMID 34191793, 2021). "The GDSC data set had a total of 47 unique drugs with ten targets, including EGFR, IGF1R, HDAC1, PARP2, AURKA, and BRAF, as well as their sensitivities across 224 cancer cell lines." (PMID 33795761, 2021). "Crosstalk between EGFR and other RTKs, such as ErbB-family members, c-Met and Insulin-like growth factor 1 receptor (IGF-1R), are vital in ascertaining the mechanisms of drug resistance in cancer treatment." (PMID 34112110, 2021). "Downstream of growth signaling (IGF-1R, EGFR), long noncoding RNA (lncRNA) H19 regulates cancer stemness and EMT markers in HepG2 and Hep3B2.1-7 cell lines." (PMID 33669204, 2021). "Researchers have also found that the differentiation of ex vivo-expanded CD34+ cells through manipulation of RAS/MAPK, IGF-1R, and TGF-β signaling pathways is an efficient approach for generating functional NK cells that can be used for cancer immunotherapy." (PMID 34804946, 2021). "For example, IGF1 can crosstalk with insulin-like growth factor 1 receptor (IGF-1R), thereby activating the mitogen-activated protein kinase (MAPK) and phosphoinositide 3-kinase (PI3K) signal pathways, and promoting cancer cell growth and survival." (PMID 34026600, 2021). "IGFBP7 is a secreted factor that suppresses cancer cells protein synthesis, growth and survival by competing with IGF1 binding to the IGF1R, thereby preventing its activation." (PMID 33673232, 2021). "Epidermal growth factor receptor (EGFR), Insulin-like growth factor -1 receptor (IGF-1R), and Vascular Endothelial Growth Factor -A (VEGF-A) are overexpressed in various human cancers including CRC." (PMID 34638601, 2021). "Several receptors, like cluster of differentiation-133 (CD133), human endothelial receptor 2 (HER2) and insulin-like growth factor 1 receptor (IGF1R), often show a overexpression on numerous types of cancer cells and cancer stem cells (CSCs)." (PMID 34915901, 2021). "Specifically, we discovered a novel protein complex, HDGF-LGR5, that adaptively responded to MAPKi to enhance cancer cell stemness, which was up- or downregulated by the inhibitors of ITGB3 + JNK or ITGB3 + IGF1R." (PMID 34106558, 2021). "A combination of curcumin and dasatinib also resulted in the downregulation of the EGFR/IGF-1R/Akt axis, further providing evidence that this may be one of the primary mechanisms of inhibition by curcumin either alone or in synergistic combination with other anti-cancer agents." (PMID 34867402, 2021). "In cancer-resistant cells, the sustained activation of the AKT/mTOR is regulated by the upregulation of IGF1R, which plays a determinate role in promoting resistance to PI3K/AKT/mTOR inhibitors." (PMID 33466806, 2021). "Insulin-like growth factor-1 receptor (IGF-1R), an important factor in promoting cancer cell growth and survival, is commonly upregulated in cancer cells." (PMID 34359752, 2021). "During hypoxia, IGF-1R expression is increased, and the downstream effector AKT is activated, leading to hypoxic cancer cell growth and survival." (PMID 34359752, 2021). "Increased IGF/IGF-1R signaling promotes sorafenib resistance through increasing the cancer stemness of cancer cells, upregulating the microRNAs, which regulate IGF/IGF1R signaling, or inducing in IGFBPs production." (PMID 33669204, 2021). "W0101 is a novel insulin-like growth factor type 1 receptor (IGF-1R)-targeting ADC, which was designed to deliver cytotoxic MMAE to the IGF-1R-overexpressing cancer cells." (PMID 34203870, 2021).
cancer (continued). "The differentiation of ex vivo expanded CD34 + cells through manipulation of RAS/MAPK, IGF-1R and TGF-β signaling pathways is an efficient approach for generating functional NK cells that can be used for cancer immunotherapy." (PMID 34098947, 2021). "A phase Ib/II clinical trial testing the combination of BYL719 and an anti-IGF1R antibody, AMG479, showed toxicity in cancer patients (NCT 01708161), but there are also other approaches to targeting the IGF2/IGF1R axis." (PMID 34067117, 2021). "The present work illustrated a comprehensive workflow for pan-cancer analysis and thoroughly investigated the role of IGF-1 and IGF-1R in cancers." (PMID 34804946, 2021). "Such a mechanism is also known for increased angiogenesis in cancer by shed SDC-1 with binding to pro-angiogenic factors such as VEGF, FGF2, insulin-like growth factor 1 receptor—IGFR1 and presenting these growth factors to their respective receptors." (PMID 33562126, 2021). "IGF1R and HER2 are two surface markers that both overexpress in various cancer types, exhibiting great research values." (PMID 34915901, 2021). "The IGF1R is a transmembrane tyrosine-kinase receptor (RTK) expressed in most tissue types, including cancer cells, and responsible for long-term actions on growth and development." (PMID 34440844, 2021). "On the other hand, IGF-1R expression positively correlates with the expression of NRP1 and CD276 in the majority of 33 cancer types." (PMID 34804946, 2021). "We also found a significant correlation between IGF1R/PCNA and RAD18/PCNA colocalization in cancer tissue, indicating a possible link to TLS activation." (PMID 32701997, 2020). "We have demonstrated that phosphorylation of multiple RTKs, such as EGFR, FGFR2, IGF1R, and MET, can be regulated by O-glycosylation in various cancers." (PMID 32005975, 2020). "In this sense, cancer cell-derived EVs containing mRNA coding for CXCR-4 and IGF-1R promote CAFs secretion of growth factors, such as VEGF in acute myeloid leukemia." (PMID 33553157, 2020). "The cross-talk between IGF-1R and GPER appears to represent a general stimulatory mechanism shared among diverse types of cancer, including mesothelioma and lung cancer." (PMID 33364239, 2020). "To study the activation of the DDT pathway in cancer tissue, we performed in situ PLA for IGF1R/PCNA colocalization in 35 tumors (29 primary and 6 metastases) from 30 patients." (PMID 32701997, 2020). "The crosstalk between EGFR and other growth factor receptors markedly enhances the progression of cancer by the transactivation of EGFR through interaction with platelet-derived growth factor (PDGFR) and IGF-1R." (PMID 32708604, 2020). "Across different types of cancer tissues, we observed that nuclear IGF1R was colocalized with PCNA, indicating that a significant proportion of human cancers depend on this mechanism for DNA damage tolerance." (PMID 32701997, 2020). "In this study we aimed to explore and describe the potential interaction between IGF1R and PCNA in cancer tissue and cancer cell lines." (PMID 32701997, 2020). "The IGF1R and IRA are both frequently overexpressed in distinct types of cancers, including breast, colorectal and prostate carcinoma." (PMID 33260481, 2020). "SUMOylation of the IGF-1R induced by IGF-1R internalization was proposed to be important, and IGF-1R translocation in cancer cells is facilitated by a specific subunit of dynactin p150Glued." (PMID 33584548, 2020). "In this regard, it is worth noting that IGF-II has been found to be able to bind and transduce signals via both the homo-tetrameric, high-affinity RTKs (IGF1R and IRA) and via its hetero-tetrameric (IGF1R/IRA) hybrid receptor in cancer." (PMID 32033443, 2020). "Unfortunately, these anti-IGF-1R agents have very limited efficacy in clinical trials, suggesting the existence of a mechanism to antagonize the IGF-1R inhibition in cancer cells." (PMID 32843616, 2020).
cancer (continued). "Following the observation of an increased IGF1R/PCNA colocalization in clinical tumors, we performed a similar PLA staining for Rad18 and PCNA on a subset of the clinical cancer panel (n = 16)." (PMID 32701997, 2020). "By computational analysis of the vast cancer genomics information in public databases (TCGA and METABRIC), we obtained evidence that high IGF-1 or IGF-1R levels correlate with a worse clinical outcome in TNBC patients." (PMID 32325700, 2020). "By interfering with ITGβ1, Src, or Cav1 activation we eliminated both the ability of TF/FVIIa to rescue cancer cells from TRAIL-induced apoptosis and the ability to induce IGF-1R-dependent protein production." (PMID 32458278, 2020). "EGR1 directly binds to the human IGF1R gene promoter, regulates its expression, activates the ERK and AKT pathways and promotes cancer cell growth." (PMID 32391121, 2020). "In situ proximity ligation assay identified frequent IGF1R and PCNA colocalization in many cancer types." (PMID 32701997, 2020). "IGF1R is a tyrosine kinase receptor that can also activate the RAS pathway and promote proliferation of cancer cells, resistance to apoptosis, and epithelial-mesenchymal transition." (PMID 32796636, 2020). "In cancer, IGF-II can act via IGF-1R and/or IR-A and these autocrine/paracrine signaling loops are regularly observed." (PMID 33053840, 2020). "Conversely, 28 of cancer-related genes were downregulated by shNrf1, of which 6 genes (i.e., HIF1A, STAT5B, IGF1R, TGFBR1, ATRN, and FZD6) were upregulated by Nrf1α−/− to varying extents." (PMID 32273945, 2020). "The demonstration that multi-engineered adjuvanted cancer cell vaccines can break the tolerance towards a highly tolerized RTK, such as IGF1R, is a valuable proof of principle." (PMID 30979001, 2019). "Previous studies indicated that IGF-1R activated AKT and sequentially up-regulated the expression of GLUT1, which promoted the glycolysis of cancer cells." (PMID 31160483, 2019). "To better define the metabolic effect of IR-A, which is the receptor principally involved in IGF2 action in cancer cells, we used MCF7 cells where the IGF1R was stably knocked-out by CRISPR/Cas technology and stably overexpressed the IR-A (MCF7IGF1R-ve/IR-A)." (PMID 31480557, 2019). "Blockage of IL6 and IGF-1R activation disrupts expression of cancer stemness properties in vitro and in vivo, indicating that the inflammatory niche of IL6 promotes early recurrence through IGF-1R activation in patients with HBV-HCC." (PMID 31505803, 2019). "The niche of IL6 stimulates the expression of IGF-1R and autocrinal IGF1 dependently in HBV-HCCs and strongly correlates with OCT4/NANOG expression, early recurrence, and cancer stemness features." (PMID 31505803, 2019). "In CRC, similarly to other cancers, IGF2 promotes cancer cell growth through several types of receptors, mainly IGF1R and AKT phosphorylation, as well as IR-A." (PMID 31623387, 2019). "It has also been reported to promote PrCa growth by binding to SRC3, an androgen receptor co-activator and inducing increased expression of IGF1R, resulting in activation of the AKT signaling pathway and cancer cell growth." (PMID 30958860, 2019). "Among the signal transduction pathways involved in adaptive cancer response to therapy are tyrosine kinase receptors (RTKs) regulated by NRP1, such as EGFR and IGF1-R, and intracellular effectors, such as PI3K/AKT, MAPK/ERK or NF-κB." (PMID 31027288, 2019). "Recently, miR-375 has been found significantly downregulated in multiple types of cancer, and suppresses core hallmarks of cancer by targeting several important oncogenes like AEG-1, YAP1, IGF1R and PDK1." (PMID 31737116, 2019). "One of the main downstream signals of IGF1R is AKT, which acts as a key regulator in cancer progression by promoting cell growth, anti-apoptotic effects, and cell invasion." (PMID 31035970, 2019).
cancer (continued). "EGFR, IGF1R, LAMA2, MYLK, PIK3CA, PIK3R1, and MYLK are members of the focal adhesion pathway, whose dynamics are highly altered in cancer cells." (PMID 31024613, 2019). "Insulin-like growth factor 1 receptor (IGF-1R) signaling is a master regulator of pathophysiological processes directing DM and cancer." (PMID 31847392, 2019). "Treatment with curcumin, as an adjuvant intervention to a chemotherapeutic regimen named FOLOX, resulted in cancer cell apoptosis through downregulating the epidermal growth factor receptor (EGFR) and IGF-1R expression." (PMID 30987250, 2019). "A receptor processing defect in IGF-1R and INSR was observed in LoVo cells, a cancer cell line reported to lack expression of the proprotein convertase furin, although no obvious decreases in the occupancy of N-glycans was noted in these cells." (PMID 31101650, 2019). "More recently, an aberrant increase of IRES-dependent translation of key cancer gene mRNAs has been reported in cancer cells, including the major angiogenic factors FGF1, FGF2 and VEGFA, as well as c-myc and insulin growth factor-like receptor (IGF1R)." (PMID 30791615, 2019). "We also noted that IGF1R is an important molecule participating in the HIF-1 signaling pathway and regulating cancer stemness." (PMID 30642292, 2019). "Multi-engineered adjuvanted cancer cell vaccines can break the tolerance towards a highly tolerized RTK, such as IGF1R." (PMID 30979001, 2019). "Activation of IGF1R is another mechanism conferring the acquired resistance against gefitinib to EGFR-amplified and EGFR-mutant cancer cell lines." (PMID 29455669, 2018). "As a downstream signaling molecule of IGF-1R, FOXC1 has been shown to have the same effect on cancer cells in terms of angiogenesis, proliferation, tumorigenesis, and metastasis." (PMID 29976975, 2018). "Pancreas is a complex tissue, and we should build on our knowledge on the impact of enhanced IGF-1R signaling on the “three-way”, insulin/IGF-driven interaction between cancer cells, endocrine pancreas, and the stroma." (PMID 29475434, 2018). "Several activators of MEK/ERK1/2 in human cancers have been identified, such as RAF1, IGF-1R and Connexin-43." (PMID 30016974, 2018). "miR-140-3p targets EGFR and IGF1R, which leads to the inactivation of the PI3K/AKT pathway which is involved in cancer cell survival and metabolism." (PMID 30559931, 2018). "More strikingly, IGF1R and HMGA2 are well documented as attractive targets for anti-cancer treatment." (PMID 29507664, 2018). "IGF1R mediates growth-promoting effects of both IGF-I and IGF-II and is highly expressed in many cancers." (PMID 29644076, 2018). "Treatment of cells with fulvestrant significantly inhibits ER-α dependent IGF-1R, phospho-IRS-1 and PDZK1 pathways regulating cancer cell invasion, survival, metastasis, angiogenesis and proliferation." (PMID 29787591, 2018). "Recently, hsa-miR-375 was found to be significantly downregulated in multiple types of cancer lines and to suppress core hallmarks of cancer by targeting several important oncogenes like AEG-1, IGF1R, and PDK1." (PMID 29930763, 2018). "In other cancer contexts, Cbl proto-oncogene C (CBLC) combines with IGF-1R and mediates receptor polyubiquitination in response to IGF-1." (PMID 30111747, 2018). "In the present study, we showed an important activation of p-ERK1/2 in both dysplastic and cancer MKR esophageal tissue, which is known to be a mitogenic signaling protein down-stream of IGF1R activation." (PMID 29662006, 2018). "Four target genes (BCL2L1, IGF1R, MAPK8, and FAS) and 5 signaling pathways (PI3K-Akt, FoxO, MAPK, pathways in cancer, and proteoglycans in cancer) were identified." (PMID 30497474, 2018). "In line with our data, a predominant cytoplasmic localization of SIRT1 has been reported in a group of cancer cells, owing to aberrant PI3K/IGF-1R signaling." (PMID 30038266, 2018).